SPAG1 (sperm associated antigen 1)
Description:
May play a role in the cytoplasmic assembly of the ciliary dynein arms (By similarity). May play a role in fertilization. Binds GTP and has GTPase activity.
Synonyms: SP75; FLJ32920; HSD-3.8; TPIS; CT140; CILD28; DNAAF13; HEL-S-268
Tractability: PROTAC: ubiquitination databases record sites on it; its protein half-life has been measured.
Gene: Protein-coding gene on chromosome 8 (100,157,906 to 100,259,278, forward strand). Ensembl gene ENSG00000104450.
Subcellular location: Cytoplasm; Dynein axonemal particle
Subcellular location (Human Protein Atlas): Cytosol; Primary cilium; Principal piece
Gene Ontology:
Biological process: axonemal dynein complex assembly; protein stabilization; single fertilization
Cellular component: cytoplasm; cytosol; protein folding chaperone complex; dynein axonemal particle
Genetic constraint (gnomAD): Loss-of-function variants: 38 observed, 45.93 expected, observed/expected ratio (o/e) 0.83, 90% interval 0.64 to 1.08. The upper end of that interval is the gene's LOEUF score, 1.08, which puts it in group 4 of 6, group 1 being the genes least tolerant of losing a copy. Missense variants: 569 observed, 606.72 expected, observed/expected ratio (o/e) 0.94, 90% interval 0.88 to 1. Synonymous variants: 226 observed, 232.12 expected, observed/expected ratio (o/e) 0.97, 90% interval 0.87 to 1.09.
Gene-disease validity (ClinGen):
ClinGen rates the evidence that SPAG1 causes each of these diseases.
primary ciliary dyskinesia 28 (autosomal recessive): Definitive.
Homologues: Orthologues: chimpanzee SPAG1 (99% identical), macaque SPAG1 (96% identical), dog SPAG1 (82% identical), pig SPAG1 (81% identical), guinea pig SPAG1 (70% identical), mouse Spag1 (69% identical), rat Spag1 (67% identical), rabbit SPAG1 (63% identical), tropical clawed frog spag1 (47% identical), zebrafish spag1a (21% identical), zebrafish spag1b (19% identical). Paralogues in human: RPAP3 (16% identical), TOMM34 (16% identical), UNC45A (12% identical), STIP1 (11% identical), UNC45B (11% identical), TTC12 (11% identical), TOMM70 (9% identical), ST13 (8% identical), SPATA16 (8% identical), STUB1 (8% identical), TTC1 (7% identical), TTC4 (7% identical), and 6 more.
Diseases named in the same sentence as SPAG1 in open-access papers:
SPAG1 is named in the same sentence as 28 diseases in open-access papers, as found by Europe PMC text mining. Sharing a sentence is not in itself a finding about the gene and the disease. The quoted sentences say what the papers report.
primary ciliary dyskinesia (5 papers, 2019 to 2025). A rare, genetically heterogeneous, primarily respiratory disorder characterized by chronic upper and lower respiratory tract disease. "In humans, mutations in SPAG1 cause primary ciliary dyskinesia (CILD28)." (PMID 31817850, 2019). "Sperm associated antigen 1 (SPAG1) is involved in the assembly of ciliary dynein arms, and mutations in its gene are known to cause primary ciliary dyskinesia, a disorder characterized by defective motile cilia and impaired cellular transport." (PMID 41373721, 2025). "SPAG1 (sperm-associated antigen 1) is one of over 50 genes whose pathogenic variants underlie primary ciliary dyskinesia (PCD; OMIM244400), an inherited disorder affecting the function of motile cilia, highly conserved organelles protruding from the surface of eukaryotic cells." (PMID 40746734, 2025). "More importantly, DNAH9, DNAH11, PIH1D3, and SPAG1 were classified as primary ciliary dyskinesia (PCD) disease genes typically with AR inheritance; PIH1D3 follows X-linked recessive (XLR) inheritance." (PMID 35877578, 2022).
acute myeloid leukemia (2 papers, 2022 to 2024). Acute myeloid leukemia (AML) is a group of neoplasms arising from precursor cells committed to the myeloid cell-line differentiation. "For instance, Sperm-associated antigen 1 (SPAG1) is widely expressed in acute myeloid leukemia (AML) patients and is associated with a poor prognosis." (PMID 38619693, 2024).
breast carcinoma (2 papers, 2017 to 2022). "Functionally, SPAG1 acts as an inhibitor of breast cancer cell proliferation and colony formation during breast cancer pathogenesis and development." (PMID 35227274, 2022).
infertile (2 papers, 2021 to 2022). "Of note, the negative association of SPAG1 with testosterone levels observed only in women (PTWMR-women=2.99×10−06) and not in men (PTWMR-men=0.18) is supported by its association with infertility in women." (PMID 35953856, 2022).
male infertility (2 papers, 2021 to 2024). The inability of the male to effect fertilization of an ovum after a specified period of unprotected intercourse. "Five other dynein preassembly genes (DNAAF1, DNAAF3, DNAAF5, SPAG1, and CFAP298 (C21orf59)) are known to be associated with PCD and putatively, male infertility." (PMID 33635866, 2021).
pancreatic adenocarcinoma (2 papers, 2020 to 2022). "For example, SPAG1 expression could be enrolled in the early spread and adverse outcome of pancreatic adenocarcinoma and prostate cancer." (PMID 35227274, 2022).
Azoospermia (1 paper, 2019). Absence of any measurable level of sperm,whereby spermatozoa cannot be observed even after centrifugation of the semen pellet. "Interestingly, we identified meiotic proteins a priori unrelated to the UPS such as DAZL (deleted in azoospermia), SPAG1 (Sperm-associated antigen 1), SPATA5/20 (Spermatogenesis-associated protein 5/20), the tudor domain proteins TDRD1/6/9, MAEL (repressor of transposable elements), and RNF17." (PMID 31437213, 2019).
esophageal cancer (1 paper, 2020). A primary or metastatic malignant neoplasm involving the esophagus. "In addition, SPAG1 and MAGEA4 are immunogenic proteins, where peptides derived from MAGEA4 significantly induced tumor-specific cytotoxic T cell response in vitro and in vivo in human esophageal cancer and SPAG1-induced humoral immune responses in certain cancers." (PMID 33287876, 2020).
Fanconi anemia (1 paper, 2022). Fanconi anemia (FA) is a hereditary DNA repair disorder characterized by progressive pancytopenia with bone marrow failure, variable congenital malformations and predisposition to develop hematological or solid tumors. "Three variants in immune genes were categorized in ClinVar as (L)P in association with the AR inheritance mode for Fanconi anemia, complementation group C (FANCC), primary ciliary dyskinesis 7 (DNAH11), and primary ciliary dyskinesis 28 (SPAG1)." (PMID 35877578, 2022). "Of note, these variants were associated with recessive inheritance for Fanconi anemia, complementation group C (FANCC), primary ciliary dyskinesis 7 (DNAH11), and primary ciliary dyskinesis 28 (SPAG1) so far." (PMID 35877578, 2022).
liver cancer (1 paper, 2020). An epithelial or non-epithelial malignant neoplasm that arises from the liver. "One of the detected CT antigens, the sperm-associated antigen 1 (SPAG1) was up-regulated in breast and liver cancers, which was consistent with the HPA data." (PMID 33287876, 2020).
pancreatic cancer (1 paper, 2013). "Similarly, significant reduction in cellular motility by wound healing assay was demonstrated by knockdown of sperm-associated antigen 1 (SPAG1) suggesting a strong association of SPAG1 with migration abilities in pancreatic cancer cells, Panc1." (PMID 24330581, 2013).
seminoma (1 paper, 2025). A radiosensitive malignant germ cell tumor found in the testis (especially undescended), and extragonadal sites (anterior mediastinum and pineal gland). "According to earlier publications, each histologic subtype has different gene signatures identified by transcriptional profiling: seminomas have overexpressed spermatogenesis-associated genes like PRAME, MAGEA4 and SPAG1 while NSGCTs have overexpressed regulatory genes such as DNMT3B and SOX2." (PMID 40011822, 2025).
cancer (4 papers, 2014 to 2022). A tumor composed of atypical neoplastic, often pleomorphic cells that invade other tissues. "Moreover, SPAG1 is an early expressed gene in pancreatic tumorigenesis and can promote the activity of cancer cells." (PMID 35227274, 2022). "These CT antigens are potential cancer-associated biomarkers, which also play an immunogenic role in tumor-specific cytotoxic T cell response and humoral immune responses as demonstrated by MAGEA4 and SPAG1." (PMID 33287876, 2020). "Previous studies have proved that SPAG1 and MAGEA4 participate in the pathogenesis and progression of certain cancers, indicating their potential role as drug targets." (PMID 33287876, 2020).
infection (1 paper, 2016). The state of being infected such as from the introduction of a foreign agent such as serum, vaccine, antigenic substance or organism. "Although there is clear evidence that immunity can be induced experimentally with p67/SPAG1, a single infection event induces very little antibody specific for p67/SPAG1 and it is not clear whether such responses play a role in immunity in animals residing in endemic areas." (PMID 27647496, 2016).
SPAG1 also shares sentences with these, for which no sentence is quoted: tumor (2 papers); asthenospermia (1); asthma (1); astrocytoma (1); autosomal dominant deafness (1); Cohen syndrome (1); glioma (1); immune disease (1); invasive ductal carcinoma (1); neurodegenerative disease (1); prostate carcinoma (1); psychiatric disorder (1); rectal cancer (1); schizophrenia (1).